KRAS (KRas proto-oncogene, GTPase)
Diseases named in the same sentence as KRAS in open-access papers (continued):
Sharing a sentence is not in itself a finding about the gene and the disease.
tumor (continued). "Along with their higher Ras activity, thoseKRas-mutated tumour cell lines showed higher cellular association ofDiI-CaP-rHDL, compared with the KRas wild-type control cell lines." (PMID 28489075, 2017). "Eight out of the 11 tumour tissues (73%) had a KRAS mutation with p.G12D (4/8, 50%) being the predominant mutation, followed by p.G12V (3/8, 38%)." (PMID 29152076, 2017). "In the remaining three patients (Patient VI, IX, and XI), there was discordance between the KRAS mutational status of primary tumor tissues and CTCs." (PMID 28468669, 2017). "In another patient, where the tumor also was determined as KRAS exon 2–4 wild type, we detected a KRAS Exon 3 mutation by cfDNA analysis already at baseline (prior 1st line therapy), namely Q61H." (PMID 28328955, 2017). "Collectively, these data suggest that tumours with KRAS mutations have increased sensitivity to the anti-proliferative effects of Selumetinib." (PMID 28931905, 2017). "A similar pattern was reported in a Chinese study where KRAS mutations were detected in 33.3% (30/90) of the CRC tumor samples using the DNA sequencing method." (PMID 28797274, 2017). "After four courses of nivolumab, the second patient (a KRAS-G12D-mutated adenocarcinoma) also reported a clinical benefit, contrasting with a worrying condensation of lung metastases and a global increase in tumor burden on the first CT-scan." (PMID 28445137, 2017). "We noted that in patients for whom KRAS mutations were detected in both tumor tissue and blood, all tumor samples were biopsied from liver metastases." (PMID 29137355, 2017). "Unlike signature A tumors, the signature B CNA patterns were quite distinct between tumor types, although some commonalities were observed including point mutations in oncogenes such as KRAS (LU and UCEC) and amplification of MYC (BRCA, LU, and OV)." (PMID 28202506, 2017). "Because the presence of the HLA-C∗08:02 allele was required for presentation of the KRAS G12D neoantigen and tumor recognition by T cells, its loss was proposed to directly enable immune evasion." (PMID 29107330, 2017). "Of the 16 tumor tissues sampled for KRAS alterations, six tissues (38 %) had nonsynonymous KRAS mutations." (PMID 27853997, 2017). "Our results suggested that somatic KRAS mutations in polyps represent a potential molecular marker for the risk of developing advanced neoplasia." (PMID 28953955, 2017). "Increased expression of annexin A1 has been shown to be correlated with KRAS mutation, suggesting that annexin A1 is specifically involved in KRAS mutation-mediated tumor development or metastasis in CRC." (PMID 28423508, 2017). "Data show that compared with Caucasians, KRAS mutations in blood samples of Asians was more accurate and sensitive when using frozen tumor tissue samples and CTC methods compared to FFPE tissue samples and ctDNA." (PMID 28415658, 2017). "The aim of this retrospective study was to establish the clinical performance of the IdyllaTM KRAS Mutation Test on FFPE tumor samples of patients with mCRC." (PMID 28201998, 2017). "cfDNA analysis showed 100% specificity and sensitivity for the BRAF V600E mutation and 98% specificity and 92% sensitivity with a concordance value of 96% for the KRAS mutation, compared with a tumor-tissue analysis." (PMID 28903450, 2017). "A previous study showed that tumor cells harboring either KRAS/BRAF mutations or EGFR amplification were slightly less sensitive to BEZ235 than other cells." (PMID 29296217, 2017). "All BRAF mutations (2 patients) were homogenous in nature, where two of six (33%) patients with a KRAS mutation having evidence of intra-tumour heterogeneity." (PMID 28097409, 2017). "Exon 2 of the KRAS gene was identified as a mutation in both cultured and tumor cells extracted from mice after induction of neoplasia." (PMID 29285236, 2017). "In two others, material from the primary tumor showed another two mutations (KRAS p.G12 V mutation and KIF5B-Ret translocation)." (PMID 28693444, 2017).
tumor (continued). "Nearly all PDAs harbor somatic KRAS mutations, nominating circulating tumor DNA (ctDNA) KRAS as an alternative disease biomarker, however, variable clinical performance has limited its clinical utility." (PMID 29228650, 2017). "In the present study, we developed the ISAD-KRAS assay to detect 2 KRAS hotspot mutations (Exon 12 & 13), and showed the sensitive and specific detection of these sequence changes in the tumor samples." (PMID 29137388, 2017). "Tumour cells with BRAF or KRAS mutations that drive strong activation of ERK1/2 typically become ‘addicted’ to the pathway for proliferation or survival." (PMID 28548464, 2017). "In one study, serial sampling of patient sera revealed that 9 out of 24 (38%) patients with initially KRAS WT tumours developed detectable mutations in KRAS between 5 and 6 months after the initiation of panitumumab monotherapy." (PMID 28593995, 2017). "Although the final Jass classification is divided into five groups, he suggested that that CIMP-High CRC was generally associated with BRAF mutations, KRAS wild type, a right colon tumour, female predominance and MSI-H." (PMID 28097409, 2017). "To specify these numbers, we calculated the overall per patient concordance of KRAS mutational status between cfDNA and tumor tissue with 80% in therapy naïve patients." (PMID 28328955, 2017). "EGFR and KRAS mutation tests are often carried out from formalin-fixed paraffin embedded (FFPE) tumor tissue samples." (PMID 28430611, 2017). "One single tumor resistant to the sequential treatment with gefitinib, afatinib and osimertinib showed the presence of KRAS-G12D mutation, the only acquired mutation with allelic frequency higher than 2% among all analyzed samples." (PMID 28416737, 2017). "The combination of multiplex iPLEX analysis and the UHS method retrieved tumor-specific KRAS mutations, which had been found in the patient tumor tissue, in plasma samples from 58.5% (62/106) of metastasis group and 16.7% (9/54) of non-metastasis group." (PMID 28459822, 2017). "This is a desirable situation within the KRAS mutated tumor for a more efficient virus-mediated cell growth inhibition." (PMID 28422714, 2017). "A higher geometric mean was representative of LAC (n=3), PDAC and CCA tumours harbouring KRAS mutations." (PMID 28220783, 2017). "We found that the KRAS rs1137188 variant AA genotype was highly associated with tumor size (≥ 5 cm) (P = 0.01; Bonferroni-adjusted P = 0.04)." (PMID 28328959, 2017). "In Round 3 of the MRR, all of the patients whose medical records were investigated had a confirmed wild-type tumour status before the initiation of panitumumab treatment, although a minority (16.8%) were only tested for KRAS mutation status." (PMID 29183279, 2017). "All KRAS mutations detected in plasma samples were concordant with those confirmed in patient-matched tumor tissue samples." (PMID 28459822, 2017). "This tumor also contained an activating KRAS alteration (p.G12D), a mutation that was also described in several KIT mutant GIST cases in a single report." (PMID 28768491, 2017). "New combinations with MAPK and PI3K pathway inhibitors are needed in tumours with mutated KRAS or BRAF, which are exclusive." (PMID 28106826, 2017). "We did not observe the occurrence of new mutations with an allelic frequency higher than 2% with the exception of one single tumor resistant to gefitinib-afatinib-osimertinib, in which the KRAS-G12D mutation was detected with an allelic frequency of 8,5%." (PMID 28416737, 2017). "Even within the metastasis group, detectable plasma KRAS mutations correlated with larger primary tumor sizes (P = 0.014) and shorter overall survival rates (P = 0.003)." (PMID 28459822, 2017).
tumor (continued). "Found in precancerous lesions, these mutations are responsible for constitutive activation of KRAS signaling and contribute to tumor development." (PMID 27602750, 2017). "Relatively low AF in the BM tumour DNA (19%) suggests that KRAS p.G13D mutation in this patient is likely subclonal." (PMID 28492226, 2017). "The presence of detectable tumor-specific KRAS mutations in the plasma correlated with heavier tumor burden." (PMID 28459822, 2017). "Thereby we identified the two common hotspot mutations BRAF V600E (c.1799 T > A;pVal600Glu; NM_004333.4) and KRAS G12D (c.35G > A;p.Gly12Asp; NM_033360.3) (8–17% of mutated reads) in 6/11 tumour samples." (PMID 29213343, 2017). "The detection of tumor-specific KRAS mutations in plasma correlated with tumor burden in this study." (PMID 28459822, 2017). "Our findings suggested that the KRAS somatic mutation would be a useful marker for predicting the development of metachronous advanced neoplasia." (PMID 28953955, 2017). "The presence of KRAS mutations in cfDNA was significantly associated with the tumour being sited at the body, tail or neck of the pancreas (p=0.015) compared to the head of the pancreas." (PMID 29152076, 2017). "The detection of tumor-specific KRAS mutations in plasma samples correlated with systemic tumor burden and earlier tumor recurrence." (PMID 28459822, 2017). "Aberrant RAS activation plays causal role in human cancer with an estimated 30% of human tumours harbouring somatic oncogenic mutations mainly in KRAS, but also in NRAS and HRAS." (PMID 28497782, 2017). "The study also evaluated the frequency of EGFR and KRAS mutations in the adenocarcinoma tumor cell line with LLC cells." (PMID 29285236, 2017). "Somatic KRAS mutations have been reported to be present in greater than 90–95% of PDA cases assessed by tumor tissue analysis suggesting a potential biomarker in detecting and monitoring disease progression." (PMID 29228650, 2017). "Tissue sections were immunohistochemically stained for pERK1/2, pAKT and pp70S6K1 as markers of pathway activation, and tumor-derived DNA was analyzed for mutational status of KRAS exon 2 and BRAF exon 15 by amplicon sequencing." (PMID 28507280, 2017). "A follow-up targeted NGS (being introduced at the time) instead detected a KRAS mutation in the tumour of the right upper lobe." (PMID 28347348, 2017). "This indicated that besides the KRAS G12D driver mutation that was present in the respective primary tumor and CTCs, there was also a tumor subclone with an ERBB3 mutation that was shed into the circulating blood." (PMID 28978093, 2017). "We also included 15 studies in which the KRAS mutation was detected by tumor tissue for prognostic subgroup analysis." (PMID 28415658, 2017). "This is a desirable situation within the KRAS mutated tumor for a more efficient virus mediated cell killing." (PMID 28422714, 2017). "We validated the KRAS mutation in the five patients by Sanger sequencing using both tumor and whole blood samples." (PMID 28462938, 2017). "The objective of our prospective study was to assess the impact of CTC counts on survival and the correlations of KRAS mutations in CTCs and corresponding primary tumor samples in patients with PDAC." (PMID 28674438, 2017). "If only one area of the tumour was tested for a KRAS mutation from each patient, there would be a 3.13% chance that the mutation would be missed, based on our 12-patient sample and the sample being divided into eight equal parts." (PMID 28097409, 2017).
tumor (continued). "A recent extensive study on distinct tumor subtypes in PDAC revealed similar results: mutations (not only KRAS) were partially diverse in the primary tumor and metastatic sites." (PMID 28674438, 2017). "Although tumor tissue is the reference standard for KRAS mutation confirmation, obtaining tissue samples is difficult, costly, and invasive." (PMID 28415658, 2017). "Further analysis of patient-derived xenografts revealed upregulation of FOSL1 expression in tumours with KRAS mutations compared to wild type." (PMID 28220783, 2017). "We performed Sanger sequencing of the KRAS gene from tumor and normal tissues, and confirmed that the G12V mutation was present only in the tumor tissue." (PMID 28462938, 2017). "To investigate the expression of autophagy-related genes in human tumours with documented KRAS mutations, we queried available RNAseq data from The Cancer Genome Atlas." (PMID 28581519, 2017). "The mechanism by which mutated KRAS coordinates the metabolic reprogramming to promote tumor growth remains to be investigated." (PMID 28749408, 2017). "Baseline characteristics of patients including gender, age, smoking history, tumor differentiation and stage were balanced matching between KRAS mutation group and EGFR/ALK/KRAS wild-type group by propensity matching score analysis." (PMID 28451792, 2017). "Oncogenic KRAS mutations are found in over 90% of PDACs, playing a central role in tumor progression." (PMID 29108249, 2017). "KRAS mutations are associated with tumor cell migration and invasion via disruption of the actin cytoskeleton and regulation of integrin expression, among other mechanisms." (PMID 29108374, 2017). "Loss of Cdc42 promoted KRAS-induced Club cell tumor formation, underscoring an important tumor initiation function of polarity loss which was previously considered a by-product of abnormal cell accumulation." (PMID 28871124, 2017). "Our analysis demonstrated more KRAS mutations in CTCs than in tumor tissues at an early stage, but lower KRAS mutations in advanced stages of CRC." (PMID 29100436, 2017). "Using this sensitive and rapid assay, we aimed to accurately and rapidly detect KRAS mutations in 70 tumor tissues from CRC patients." (PMID 29137388, 2017). "Reciever operating curves were then created for EMVI (Area under curve (AUC) = 0.95), LVI (AUC 0.97), tumour differentiation (AUC 0.95) and KRAS mutation status (AUC 1.0)." (PMID 28827587, 2017). "We selectively chose portions of the surgical specimen with high tumor purity to allow for confirmatory KRAS mutation analysis using Sanger sequencing." (PMID 28125707, 2017). "Second, the heterogeneity of KRAS mutation status within the primary tumor is a well-known phenomenon." (PMID 28674438, 2017). "Discordance in the detection of EGFR and KRAS mutations between the primary tumor and corresponding metastases has been shown to be as high as 28% and 24% in 25 patients with metastatic NSCLC, respectively." (PMID 29290998, 2017). "In fact, 3 of the 5 tumours (60%) that showed a significant anti-proliferative response uniquely at 0.1 μM Selumetinib (Subset 2) had KRAS or BRAF mutations." (PMID 28931905, 2017). "This is also supported by in vitro study showing that KRAS mutant tumours are more susceptible to HSPC1 inhibitions via degradation of STK33." (PMID 28255900, 2017). "IDF-11774 exhibited strong efficacy in inhibiting the growth of A549 cell tumor, which contain a KRAS mutation." (PMID 28569777, 2017). "KRAS mutations detected in plasma were concordant with those confirmed in patient-matched tumor tissue in most cases but, in one patient, KRAS G13D mutation was detected in plasma but KRAS G12D mutation was in matched tumor tissue." (PMID 28459822, 2017). "The CIMP-L subtype, defined as tumours with 1/5 to 3/5 of these marker genes methylated, is associated with KRAS mutations and is more common in men." (PMID 28351398, 2017).
tumor (continued). "When these areas are compared to the CIMP status of those tumours, the KRAS mutation is seen in areas of hypermethylation." (PMID 28097409, 2017). "Patient 45 was the only case that had two different KRAS mutations detectable by tNGS in the same tumour tissue region, p.G12D (VAF=17%) and p.G12C (VAF=15.4%)." (PMID 29152076, 2017). "The study included cells which overexpress HER1 or HER2, others which don ́t overexpress any of the receptors, and also tumor cells with constitutive KRAS mutation." (PMID 29137309, 2017). "Another similar study has confirmed the tumor suppressive role of PTEN in mice with the KRAS mutation." (PMID 28383487, 2017). "In almost all samples derived from different EGFR inhibitor resistant tumors, protein levels of phospho-MAPK were low, with the exception of the one tumor resistant to gefitinib-afatinib-osimertinib, in which we detected the KRAS-G12D mutation." (PMID 28416737, 2017). "Among these genetic alterations, mutations in the KRAS gene, which often are already present in precursor lesions, play an important role in tumor development and progression." (PMID 28549417, 2017). "Constitutive KRAS signaling is a prevalent phenomenon that occurs in diverse tumor types and is associated with transformation, proliferation, and reduced sensitivity to conventional chemotherapy." (PMID 28422714, 2017). "For each patient sample, the expected mutation status was determined in the primary tumor DNA via conventional Cycleave assays or the SARMS assay for EGFR or KRAS mutations, respectively." (PMID 28625519, 2017). "Tumor-specific KRAS mutations were detected in 39.6% (42/106) of patients with distant metastasis, and in 5.6% (3/54) of patients without distant metastasis." (PMID 28459822, 2017). "KRAS mutations are detected in ~30% of early neoplasms with the frequency rising to ~95% in advanced PC." (PMID 28383487, 2017). "Single CTCs and tumor tissue samples were examined for mutations in codons 12 and 13 of the KRAS gene." (PMID 28468669, 2017). "Of the 71 patients who were treated with concurrent oxaliplatin-containing chemotherapy, all had tumours with either a confirmed wild-type RAS or KRAS mutation status before their first dose of panitumumab." (PMID 29183279, 2017). "Using this approach, we were able to characterize ctDNA and total cell-free DNA (cfDNA) kinetics by selective amplification of KRAS mutated DNA fragments in the blood plasma over the course of tumour resection and the surrounding days." (PMID 28827745, 2017). "By comparing the differences between the tumor progression and the stable cohorts in CTCs with KRAS mutation, the risk ratio associated with different tumor status was 1.59 (95% CI; 0.69, 3.69)." (PMID 29100436, 2017). "One notable finding from our current study was the ability of dPCR to detect more than one KRAS mutation subtypes within a tumor, depicting the presence of intratumoral heterogeneity using only FNA biopsy specimens." (PMID 28125707, 2017). "They found EGFR gene deregulation in 25 out of 36 primary tumours and 29 out of 36 metastases, KRAS mutations in 16 out of 37 cancers and in 15 out of 37 metastases, and BRAF mutations in 2 out of 36 cancers and 2 out of 36 metastases." (PMID 28097409, 2017). "The median sequencing coverage for KRAS mutations in tumor tissue sequenced using the FoundationOne panel was 845x, with only one sample below 500x, in line with the analytical validation study published by Foundation Medicine." (PMID 29137355, 2017). "Although the results of the KRAS mutational analysis of the primary tumor usually match with the metastases in only 5 to 10% of the cases, the KRAS mutational status is heterogeneous between the primary tumors and the metastases." (PMID 28580315, 2017).